TRAV13-2 (T cell receptor alpha variable 13-2)
Description:
V region of the variable domain of T cell receptor (TR) alpha chain that participates in the antigen recognition. Alpha-beta T cell receptors are antigen specific receptors which are essential to the immune response and are present on the cell surface of T lymphocytes. Recognize peptide-major histocompatibility (MH) (pMH) complexes that are displayed by antigen presenting cells (APC), a prerequisite for efficient T cell adaptive immunity against pathogens. Binding of alpha-beta TR to pMH complex initiates TR-CD3 clustering on the cell surface and intracellular activation of LCK that phosphorylates the ITAM motifs of CD3G, CD3D, CD3E and CD247 enabling the recruitment of ZAP70. In turn ZAP70 phosphorylates LAT, which recruits numerous signaling molecules to form the LAT signalosome. The LAT signalosome propagates signal branching to three major signaling pathways, the calcium, the mitogen-activated protein kinase (MAPK) kinase and the nuclear factor NF-kappa-B (NF-kB) pathways, leading to the mobilization of transcription factors that are critical for gene expression and essential for T cell growth and differentiation. The T cell repertoire is generated in the thymus, by V-(D)-J rearrangement. This repertoire is then shaped by intrathymic selection events to generate a peripheral T cell pool of self-MH restricted, non-autoaggressive T cells. Post-thymic interaction of alpha-beta TR with the pMH complexes shapes TR structural and functional avidity.
Synonyms: TCRAV13S2; TCRAV8S2; TRAV132
Gene: T-cell receptor variable (V) gene on chromosome 14 (21,918,188 to 21,918,756, forward strand). Ensembl gene ENSG00000211791.
Subcellular location: Cell membrane
Gene Ontology:
Biological process: response to bacterium
Cellular component: plasma membrane
Homologues: Orthologues: mouse Trav5-1 (59% identical), mouse Trav10n (57% identical), mouse Trav5d-4 (57% identical), mouse Trav5n-4 (57% identical), mouse Trav10 (56% identical), mouse Trav10d (56% identical), mouse Trav5-4 (56% identical), rat AABR07017838.1 (54% identical), rat AABR07017874.1 (54% identical). Paralogues in human: TRAV13-1 (63% identical), TRAV5 (58% identical), TRAV21 (36% identical), TRAV17 (35% identical), TRAV20 (35% identical), TRAV36DV7 (35% identical), TRAV39 (35% identical), TRAV6 (35% identical), TRAV7 (34% identical), TRAV38-1 (32% identical), TRAV25 (31% identical), TRAV38-2DV8 (31% identical), and 11 more.
Diseases named in the same sentence as TRAV13-2 in open-access papers:
TRAV13-2 is named in the same sentence as 1 disease in open-access papers, as found by Europe PMC text mining. Sharing a sentence is not in itself a finding about the gene and the disease.
TRAV13-2 shares sentences with these, for which no sentence is quoted: thymoma (1 paper).